MET (MET proto-oncogene, receptor tyrosine kinase)
Diseases named in the same sentence as MET in open-access papers (continued):
Sharing a sentence is not in itself a finding about the gene and the disease.
tumor (continued). "Growths of two (gastric, colon) METex14del+ patient tumor derived cell lines were profoundly inhibited by both MET tyrosine kinase inhibitors and a monoclonal antibody targeting MET." (PMID 26375439, 2015). "MET, as a member of receptor tyrosine kinase (RTK) family, plays a causal role in tumor cell survival, growth, angiogenesis and metastasis." (PMID 26528757, 2015). "Next, we assessed MET protein expression levels in 9 available tumor sections by IHC and evaluated the relationship between the expression of MET and GCNs." (PMID 25886066, 2015). "MET gene amplification and protein overexpression have been shown to lead to constant activation of the MET signaling pathway which contributes to tumor growth, angiogenesis and metastasis." (PMID 26587992, 2015). "Accordingly, our previous studies demonstrated that RH30 ARMS cells with silenced MET level displayed diminished tumor growth and metastasis." (PMID 26384300, 2015). "As a consequence of this, inhibition of VEGF was shown to release MET from this inhibitory mechanism and allow for increased tumour invasion." (PMID 24482243, 2014). "In fact, MET overexpression or genetic alteration has been shown to play a role in the pathogenesis of several tumor types." (PMID 24500024, 2014). "The HGF/MET signaling axis appears to play an important role in the development and malignant progression of gastroesophageal cancers, particularly in tumor invasiveness and metastasis." (PMID 24930887, 2014). "Demonstration of co-expression of SF/HGF and c-MET by immunohistochemistry in the same tumor population seems to support that a subset of SCLC gains cell proliferation through an autocrine stimulatory mechanism." (PMID 25314153, 2014). "In RMS, miR-1/206 suppresses MET expression and functions as a potent tumor suppressor in MET-overexpressing tumors." (PMID 24743780, 2014). "It strongly inhibited MET phosphorylation and tumor growth in S114, U-87MG and NCI-H441 xenografted mice models." (PMID 25110867, 2014). "We also investigated c-MET activation in Hewga-CCS tumor tissues and found that pazopanib inhibited c-MET phosphorylation in Hewga-CCS xenografts." (PMID 24946937, 2014). "In cancer tissues, tumor cells play a role in inducing HGF/SF expression by stromal fibroblasts, whereas fibroblast-derived HGF/SF leads to invasive growth of tumor cells through MET." (PMID 25268161, 2014). "Perturbation of HGF/MET signaling with anti-HGF antibodies or MET kinase inhibitors attenuates both tumor growth and metastatic dissemination in both GEC cell lines and animal models." (PMID 24930887, 2014). "In a Phase I clinical trial currently ongoing in subjects with advanced solid tumors, it is well tolerated and has demonstrated promising anti-tumor activity in patients carrying the MET gene amplification." (PMID 28548076, 2014). "Higher MET gene copy number in the primary tumor at the time of diagnosis predicts worse outcome in patients with NSCLC." (PMID 25232729, 2014). "Single-chain variable fragment (scFv) anti-MET antibody-pegylated liposomes were also shown to display anti-tumor activity “in vivo”." (PMID 28548076, 2014). "Since MET/HGFR is often over-expressed and/or aberrantly activated in tumors, monoclonal antibodies can be used as probes for MET detection or as “bullets” to target MET-expressing tumor cells, thus pointing to their use in diagnosis and therapy." (PMID 28548076, 2014). "For the purposes of determining eligibility, a MET positive tumor is defined when ≥50% of malignant cells express MET (cytoplasmic and/or membranous staining) at weak, moderate or strong intensity." (PMID 24930887, 2014). "Oral administration of EMD1214063 resulted in a strong inhibition of MET-driven tumor xenografts in mice." (PMID 25110867, 2014). "For example, different cut-off values have been used to determine a positive result, such as MET expression in >10% of tumor cells or MET expression in >30% of tumor cells." (PMID 24465403, 2014).
tumor (continued). "The same biological responses that are strictly regulated by HGF in MET-expressing cells in normal or repairing physiological settings can be subverted and become responsible for tumor development and metastasis." (PMID 28548076, 2014). "For subgroup analyses based on race and tumor stage, all the results are suggesting that MET overexpression had a significant poor impact on survival." (PMID 24416238, 2014). "In preclinical GEC models, abrogation of HGF/MET signaling has been shown to induce tumor regression as well as inhibition of metastatic dissemination." (PMID 24930887, 2014). "The role of MET amplification has been most extensively correlated with tumor invasion and aggressive metastatic behavior in gastrointestinal malignancies." (PMID 25593979, 2014). "Increasing evidence has demonstrated a link between c-MET overexpression and increased tumor cell metastasis and invasion." (PMID 25009663, 2014). "Since identification of tumours most likely to respond to MET pathway blockade is a key component of therapeutic development, we also discuss the issues and challenges associated with identification of MET biomarkers to aid patient selection." (PMID 24930887, 2014). "Out of those, 6 used FISH and the remaining 3 used RT PCR to assess the MET gene copy number in the primary tumor." (PMID 25232729, 2014). "Ten variants were identified from eight genes in both the tumor and normal groups (APC, EGFR, FGFR3, KDR, MET, PDGFRA, RET and SMO)." (PMID 25404506, 2014). "MET has a significant role in tumor cell growth, thus providing a strong rationale for targeted therapy in cancer." (PMID 25110867, 2014). "Treatment of MET-expressing cancer cell lines with tivantinib inhibited cell proliferation, induction of caspase-dependent apoptosis and growth inhibition of tumor cells in xenografted mice." (PMID 25110867, 2014). "This study was the first to demonstrate that transfer of the MET oncoprotein from tumor-derived exosomes to bone marrow progenitor cells promote the metastatic process in vivo." (PMID 24424657, 2014). "Peripheral edema has been associated with treatment with all monoclonal antibodies targeting HGF or MET in combination with various cytotoxic and targeted therapies across multiple tumor types." (PMID 24930887, 2014). "We propose that the anti-VEGFR2 activity of cabozantinib results in a restoration of the blood-brain barrier, thereby precluding an efficient distribution of the compound to the tumor cells and reducing c-MET inhibitory activity." (PMID 23484006, 2013). "In the current manuscript, we aim to review the current data linking MET and tumor cells response to IR." (PMID 24378750, 2013). "Tumor hypoxia is believed to be correlated with increased metastatic potential, via the regulation of αvβ3 integrin expression and promotion of tumor invasion by the tyrosine kinase receptor MET." (PMID 23426939, 2013). "The combinatorial approach decreased cell proliferation and tumor volumes compared to IR or c-MET inhibition alone, highlighting the synergistic benefit of combined treatment." (PMID 23579692, 2013). "The paracrine loop between HGF-producing stroma and MET-expressing tumor cells acts as a local switch for the invasive phenotypes, as follows." (PMID 23296269, 2013). "The exact contribution of c-MET during tumor progression in E98 xenografts is somewhat difficult to assess." (PMID 23484006, 2013). "MET/HGF overexpression patterns have been reported to correlate with increased tumor growth rate and metastasis and overall poor prognosis." (PMID 24378750, 2013). "Among different intracellular signalling transduction pathways, the hepatocyte growth factor (HGF) HGF/MET system is a key driver of oncogenesis and tumor progression in several human malignancies." (PMID 24260160, 2013).
tumor (continued). "MET activation drives the malignant progression of several tumor types, including colorectal cancer (CRC), by promoting signaling cascades that mainly result in alterations of cell motility, survival, and proliferation." (PMID 24005867, 2013). "The discovery of NK4 prompted researchers to search HGF-antagonists and MET-inhibitors as anti-tumor drugs." (PMID 23296269, 2013). "By upregulating hypoxia-inducible factor, hypoxia results in increased HGF expression in tumor and surrounding normal interstitial cells and increased MET expression in tumor and endothelial cells." (PMID 23606971, 2013). "These loci are respectively known to harbour tumour-associated genes, including TIF, BRAF, MLL3, SMO, and MET." (PMID 24289252, 2013). "c-MET is considered a possible therapeutic target in numerous tumor types and is also a candidate regulator of response to anti-HER2 and anti-epidermal growth factor receptor (EGFR) therapy." (PMID 23251249, 2013). "Two current strategies for patient selection based on tumor biomarkers are quantification of tumor cMET content via immunohistochemical (IHC) and immunoassay tissue analysis and assessment of MET sequence status." (PMID 23606971, 2013). "Since the microenvironment influences the gene expression profiles of tumor cells, we also analyzed the MET expression levels by metastatic site." (PMID 24205338, 2013). "There are now numerous reports showing that HGF-antagonists and MET-inhibitors are logical for inhibiting tumor growth and metastasis." (PMID 23296269, 2013). "Often, heterogeneity in c-MET expression is found between tumor cells and some papers have reported on the expression of c-MET on endothelial cells too." (PMID 23484006, 2013). "Despite being tightly regulated, HGF/MET signaling contributes to oncogenesis and tumor progression in numerous cancers." (PMID 24378750, 2013). "Higher expression of c-MET in tumor tissue can lead to scattering, angiogenesis, proliferation, enhanced cell motility, invasion, and eventually, metastasis." (PMID 23593387, 2013). "Apart of its role in tumor pathogenesis, MET/HGF deregulated function emerges as an important resistance mechanism to targeted therapies against other oncogene systems such as that of the epidermal growth factor receptor (EGFR)." (PMID 24378750, 2013). "We have recently found a novel role for tumour-secreted exosomes promoting a pro-metastatic phenotype of bone marrow progenitor cells through the MET oncogene in a process called “education”." (PMID 26082317, 2013). "The high expression and activation levels of c-MET in diffuse E98 tumor areas supports the notion that c-MET is actively involved in tumor cell migration." (PMID 23484006, 2013). "Activation of MET signaling promotes tumor cell growth, survival, migration, and invasion as well as tumor angiogenesis." (PMID 23327903, 2013). "Using NK4 in a mouse model of carcinoma, we firstly found in 1998 that MET inhibition by an HGF-antagonist inhibits tumor invasive growth in vivo." (PMID 23296269, 2013). "Our data suggest that c-MET-dependent activation of signalling pathways influence the behaviour of cells within the tumour microenvironment." (PMID 26082317, 2013). "For all these reasons, the maintenance of gefitinib after tumor progression emerges as an important new therapeutic strategy to inhibit EGFR-mediated aggressive behaviour in NSCLC with MET amplification." (PMID 24167634, 2013). "Compare with NaBu treated intact cells, or with MET knock down cells, tumor volume was significantly smaller in NaBu treated MET knock down cell transplanted group." (PMID 22253909, 2012). "HSP90 is also involved in tumor cell migration through client proteins including c-MET, SRC and FAK." (PMID 22439642, 2012). "For example, the tumor suppressive function of miR-1 is partially accounted for by its repression of the oncogenic target met proto-oncogene (MET) in lung cancer, HCC, papillary thyroid cancer and RMS." (PMID 22308266, 2012).
tumor (continued). "When HGF binds to the c-MET receptor it generates MET autophosphorylation leading to activation of the MET pathway enabling cell mobilization and vascularization – two processes that contribute to tumor malignancy." (PMID 22363766, 2012). "BRAF, NRAS and MET mutations were detected in 5 (50%), 3 (30%) and 1 (10%) of 10 FFPE tumor specimens, respectively, and 3 (20%), 2 (13.3%) and 2 (13.3%) of 15 cpDNA samples, respectively." (PMID 23144797, 2012). "These c-MET mAbs were tested for binding specificity and anti-tumor activity using a range of cell-based techniques and in silico modeling." (PMID 22511956, 2012). "The two mechanisms by which TIMP-1 interferes with the metastatic potential of a tumor cell can be demonstrated by the example of the HGF receptor MET." (PMID 22807917, 2012). "In breast tumor patient, the relationship between c-MET up-regulation and tumor progress has been demonstrated." (PMID 22253909, 2012). "The data identified several kinases that are up-regulated in tumor cells, including; MET, PFTK1, BUB1, CKS1B, EIF2AK2, and NEK2." (PMID 22280838, 2012). "Again, the MET knock down resulted in a comparable tumor incidence rate with con siRNA treated control group." (PMID 22253909, 2012). "On the 30th day, the tumor incidence in NaBu- resistant MET knock down group was decreased to 18% as compared to con siRNA transfected cells." (PMID 22253909, 2012). "Our results demonstrated that when cancer cells after treated by the combination of NaBu and MET siRNA, decreased tumor incidence dramatically in the mouse model." (PMID 22253909, 2012). "The results showed the protein levels of EGFR and AKT were decreased in the tumor homogenates in both curcumin alone and curcumin combined with gefitinib groups, whereas, the c-MET, cyclin D1, and PCNA were also down-regulated simultaneously." (PMID 21858220, 2011). "For analyzing the role of c-MET in tumour-formation in vivo, we infected DU145 cells with lentivirus expressing shRNA targeting c-MET receptor and selected three c-MET negative clones." (PMID 22110593, 2011). "Because of these migratory effects of HGF/MET signaling, the role of this signaling pathway in tumor cell metastasis has been examined." (PMID 21253475, 2011). "The pattern of p-MET staining was membranous and varied from a few cells showing positivity to diffuse staining in other tumours." (PMID 21847116, 2011). "An understanding of signal transduction in tumours with MET amplification will thus be important for further development of MET-targeted therapy." (PMID 21847121, 2011). "We utilized the same NSCLC tumor panel that was used for the evaluation of the c-MET proximity assay to evaluate the HGF proximity assay." (PMID 21283737, 2011). "MET expression has been previously reported in non-tumour lung tissue and, in a similar manner of what we report here, specifically a weak expression in the basal aspect of the bronchial epithelium." (PMID 21847116, 2011). "Its mediation of efficient tumour-formation in vivo and predominant receptor expression at the invasive front implicate that c-MET regulates tumour infiltration in surrounding tissues putatively by acquisition of a stem-like phenotype." (PMID 22110593, 2011). "In this study, we performed molecular profiling of normal liver and tumor tissues from the c-MET driven mouse model, to understand the molecular changes in these mice." (PMID 21949730, 2011). "Among the genes identified in this signature, we noted, consistent with our earlier analyses, GATA3 and MET enrichment in subgroup 10 and 7 tumors, respectively, both of which are known to be preferentially expressed in luminal and basal tumor, respectively." (PMID 21672245, 2011). "A total of 58 (75.3%) specimens showed any grade of MET expression and 42 (54.5%) were considered as tumours with MET overexpression." (PMID 21847116, 2011). "The MET staining was consistently observed in the membrane of tumour cells, and the expression was diffuse in the tumour." (PMID 21847116, 2011).
tumor (continued). "These NSCLC tumor samples displayed a ∼20-fold range of c-MET levels while isotype matched controls generated less than 10% of the c-MET specific signal." (PMID 21283737, 2011). "The present study shows that the mouse c-MET tumor model has similarities with human HCC at the molecular level including down-regulation of metabolic processes and up-regulation of cell cycle genes." (PMID 21949730, 2011). "Knock-down of c-MET by shRNA infection resulted in significant reduction and delay of orthotopic tumour-formation in male NMRI mice." (PMID 22110593, 2011). "Taken together, functional c-MET mediated efficient tumour formation in parental DU145 (p<0.02) and resulted in significantly larger tumours in control DU145 cells (p<0.001)." (PMID 22110593, 2011). "Due to the low abundance of phosphorylated c-MET protein in tumor samples, c-MET was immunoprecipitated prior to immuno-detection by Western blot." (PMID 21283737, 2011). "Tumours with MET amplification are highly dependent on MET signalling for their progression, and several small-molecule inhibitors of MET have been developed and found to manifest marked antitumour efficacy both in vitro and in vivo." (PMID 21847121, 2011). "The perimeter contained more high c-MET expressing cells than the tumour centre in 27 cases (73.0%)." (PMID 22110593, 2011). "As MET phosphorylation seems to be a good indicator of the activation of the MET pathway, we explored the implication of the expression of this marker in tumour samples." (PMID 21847116, 2011). "Total MET staining was faintly detected in non-tumour epithelial cells in 67 (98%) specimens and p-MET staining in 16 (24%)." (PMID 21847116, 2011). "c-MET is one of the key players in the processes of dissociation, angiogenesis, and migration of tumour cells in HCC." (PMID 21955323, 2011). "This stresses the importance of HGF paracrine/endocrine function in MET mutant tumours that is involved in angiogenesis, growth, migration and invasion and the potential role of MET inhibitors in cases with MET mutations." (PMID 21847116, 2011). "In another study, c-MET phosphoryaltion was reduced in the post-operative tumor biopsies of patients treated with a c-MET kinase inhibitor (ARQ197)." (PMID 21283737, 2011). "Optimisation of the clinical efficacy of such drugs will require further characterisation of MET signal transduction in tumours with MET amplification." (PMID 21847121, 2011). "Their findings also suggest that the GPX3 tumor suppressor activity seems to involve transcriptional regulation of the tumor oncogene, MET." (PMID 21106063, 2010). "The other target genes, FLT3, CSF1R, PDGFRB, AXL and MET showed lower expression levels in the tumor tissue compared to normal tissue except AXL in NF1 associated GIST." (PMID 21171987, 2010). "We took advantage of gastric MET-addicted tumor cell lines that stop proliferating upon treatment with specific MET inhibitors." (PMID 20500904, 2010). "After one week, half of the mice of each experimental group (Mock, EGFR-L858R and TGFα) received doxycycline to silence MET in the tumor." (PMID 20500904, 2010). "Of note, a second tumor with focal MET amplification, GBM.18, was classified here and showed extremely high levels of PDGFB and associated signaling." (PMID 19915670, 2009). "Dysregulation of the MET–HGF signalling axis upregulates diverse tumour cell functions, including cell proliferation, survival, cell scattering and motility, epithelial-mesenchymal transition, angiogenesis, invasion, and metastasis." (PMID 19238632, 2008). "Adjacent to the main tumor xenograft, we observed human c-MET and uPAR staining of cells invading the normal brain parenchyma showing that DBM2 cells are highly invasive." (PMID 19055779, 2008). "To understand better the role of the in vivo c-MET/HGF signalling in SCLC tumour tissues, we performed IHC analysis in SCLC tumours, as established on a tissue microarray." (PMID 17667909, 2007).